RN7SL134P (RNA, 7SL, cytoplasmic 134, pseudogene)
Gene: Miscellaneous RNA gene on chromosome 16 (82,844,455 to 82,844,757, forward strand). Ensembl gene ENSG00000263360.
Homologues: Orthologues: macaque Metazoa_SRP (69% identical). Paralogues in human: RN7SL774P (82% identical), RN7SL811P (82% identical), Metazoa_SRP (82% identical), Metazoa_SRP (81% identical), RN7SL154P (81% identical), RN7SL784P (81% identical), Metazoa_SRP (80% identical), RN7SL474P (80% identical), RN7SL96P (80% identical), RN7SL123P (78% identical), Metazoa_SRP (78% identical), RN7SL163P (78% identical), and 713 more.